RNU6-329P (RNA, U6 small nuclear 329, pseudogene)
Gene: Small nuclear RNA gene on chromosome 9 (102,256,604 to 102,256,710, forward strand). Ensembl gene ENSG00000238882.
Homologues: Orthologues: chimpanzee U6 (99% identical), macaque U6 (92% identical), guinea pig U6 (91% identical), rabbit U6 (90% identical), guinea pig U6 (89% identical), guinea pig U6 (85% identical), mouse Gm22127 (85% identical), dog U6 (81% identical), mouse Gm25416 (79% identical), mouse Gm23538 (76% identical), rat LOC120097317 (71% identical), pig U6 (69% identical). Paralogues in human: RNU6-1060P (90% identical), RNU6-17P (90% identical), RNU6-18P (90% identical), RNU6-33P (90% identical), RNU6-1 (89% identical), RNU6-1011P (89% identical), RNU6-116P (89% identical), RNU6-12P (89% identical), RNU6-13P (89% identical), RNU6-15P (89% identical), RNU6-2 (89% identical), RNU6-22P (89% identical), and 1287 more.